RNU6-628P (RNA, U6 small nuclear 628, pseudogene)
Gene: Small nuclear RNA gene on chromosome 8 (123,262,843 to 123,262,949, forward strand). Ensembl gene ENSG00000222607.
Homologues: Orthologues: chimpanzee U6 (98% identical), macaque U6 (97% identical), pig U6 (79% identical). Paralogues in human: RNU6-703P (81% identical), RNU6-1123P (78% identical), RNU6-11P (78% identical), RNU6-336P (78% identical), RNU6-37P (78% identical), RNU6-41P (78% identical), RNU6-543P (78% identical), RNU6-797P (78% identical), RNU6-879P (78% identical), RNU6-1122P (77% identical), RNU6-115P (77% identical), RNU6-1329P (77% identical), and 1284 more.